STAT3 (signal transducer and activator of transcription 3)
Diseases named in the same sentence as STAT3 in open-access papers (continued):
Sharing a sentence is not in itself a finding about the gene and the disease.
T-cell acute lymphoblastic leukemia (6 papers, 2016 to 2023). Acute lymphoblastic leukemia of T-cell origin. "Furthermore, combined inhibition of phosphoinositide 3-kinase and STAT3 significantly suppressed proliferation of PTEN-mutant T-cell acute lymphoblastic leukemia both in culture and in mouse xenografts." (PMID 27672444, 2016).
thrombosis (6 papers, 2020 to 2024). "By inhibiting mitochondrial STAT3 to elicit Mito-ROS generation, C5a triggers the generation of NETs to promote the development of arterial thrombosis." (PMID 35488279, 2022). "Here, we report the case of a 26 year old male who developed an acute ST-elevation myocardial infarction due to coronary artery ectasia and thrombosis, occurring despite pediatric allogeneic HSCT for STAT3-HIES and a predicted 10-year conventional cardiovascular risk of 0.1%." (PMID 33014947, 2020).
acute GVHD (5 papers, 2016 to 2023). "Blockade of PD-L1/PD-1 interactions by anti–PD-L1 or anti–PD-1 resulted in lethal acute GVHD in recipients given STAT3–/– donor T cells." (PMID 37526084, 2023). "STAT3 (Tyr705) responses were stronger for patients with previous acute GVHD; CD3+CD4+ cells from GVHD patients showed an additional STAT3 (Ser727) response, whereas patients without acute GVHD showed additional mTOR (Ser2448) responses." (PMID 35566660, 2022). "The responses of AKT (Thr308), mTOR (Ser2448) and STAT3 (Ser727) were generally stronger for patients with previous acute GVHD; i.e., usually highly significant responses for all three phosphosites and all three cell subsets." (PMID 35566660, 2022). "Degradation of STAT3 in donor T cells prevents acute GVHD in a PD-1–dependent manner." (PMID 37526084, 2023). "Furthermore, STAT3-phospho-(Tyr705) is increased in circulating CD4+ T cells from allotransplant recipients prior to the onset of acute GVHD and seems to induce differentiation of pro-inflammatory Th17 cells and inhibition of Treg development." (PMID 35566660, 2022). "Additionally, Th17 pathogenicity has been linked to STAT3 signaling through IL23R, prompting investigation into the role of IL-23R in acute GVHD." (PMID 34722316, 2021). "However, administration of antioxidant reagents NAC or MnTBAP had no clearly demonstrable effects, suggesting enhanced function of STAT3–/– T cells to cause GVHD in vivo, although previous studies showed that antioxidants augmented acute GVHD induced by WT T cells." (PMID 37526084, 2023). "However, prevention of acute GVHD by STAT3 deficiency in donor T cells did not prevent reduction of donor T cell diversity, and induction of acute GVHD by STAT3–/–PD-1–/– T cells did not further reduce donor T cell diversity." (PMID 37526084, 2023). "However the effects of STAT3 activation are difficult to predict, and additional studies are needed to clarify the molecular mechanisms behind and the functional effects of the altered/increased IL-6 responsiveness in patients with previous acute GVHD." (PMID 35566660, 2022). "Consistently, STAT3–/– donor T cells induced lethal acute GVHD in PD-L1–/– recipients, but not in WT recipients." (PMID 37526084, 2023). "Thus, post-transplant T cells derived from patients with and without previous acute GVHD show similar STAT3 (Tyr727) phosphoresponses to IL-6, whereas STAT3 (Ser727) and mTOR (Ser2448) responses differ between the two patient subsets." (PMID 35566660, 2022). "To conclude, circulating T cells as well as CD3− cells derived from allotransplant recipients with previous acute GVHD showed generally stronger PMA phosphoresponses for AKT (Thr308), mTOR (Ser2448) and STAT3 (Ser727), than T cells from patients without previous GVHD." (PMID 35566660, 2022).
alcoholic liver diseases (5 papers, 2017 to 2025). A disorder caused by damage to the liver parenchyma due to alcohol consumption. "Studies have shown that increased expression of Stat3 in human alcoholic liver disease patients can further reduce alcoholic liver injury and inflammation." (PMID 36901774, 2023). "Upregulation of Nogo-B was also found in HCCs to stimulate the IL-6/STAT3 pathway and alcoholic liver disease through the regulation of M1 polarization of Kupffer cells." (PMID 31358770, 2019). "In animal models of alcoholic liver disease, HSYA regulates the STAT3/NF-κB signaling pathway, inhibits inflammatory cascade reactions, reduces lymphocyte infiltration and inflammatory damage, activates the Keap1/Nrf2 pathway, and reduces oxidative damage." (PMID 40584613, 2025).
Alport syndrome (5 papers, 2020 to 2023). A rare renal disease characterized by glomerular nephropathy with hematuria progressing to end-stage renal disease (ESRD), frequently associated with sensorineural deafness, and occasionally with ocular anomalies. "Several studies indicated to the role of JAK/STAT signaling pathway in the renal corpuscles in other renal disease models (via STAT3), such as in experimental nephrotic syndrome, unilateral ureteral obstruction, and Alport syndrome." (PMID 36117389, 2022). "STAT3 and IL6 were found to be increased in mice with Alport syndrome before anti-miR-21 treatment; the group, therefore, investigated the impact of STAT3 and IL6 inhibitors in Alport mice." (PMID 31044288, 2020).
amyotrophic lateral sclerosis (5 papers, 2017 to 2023). Amyotrophic lateral sclerosis (ALS) is a neurodegenerative disease characterized by progressive muscular paralysis reflecting degeneration of motor neurons in the primary motor cortex, corticospinal tracts, brainstem and spinal cord. "IL-6/STAT3 signaling inactivation in FAPs counteracted muscle atrophy and fibrosis in mouse models of acute denervation and amyotrophic lateral sclerosis (ALS)." (PMID 31114509, 2019). "CRLF3 has been associated with signal transducer and activator of transcription 3 (STAT3) activation, cell cycle regulation, neuronal morphology, and amyotrophic lateral sclerosis." (PMID 31680856, 2019). "Here the authors identify a pathway via neuronal EphB1 that induces neuroprotective signalling in astrocytes through ephrin-B1 mediated STAT3 activation, which is impaired in models of amyotrophic lateral sclerosis." (PMID 29079839, 2017).
anaphylaxis (5 papers, 2019 to 2024). An acute hypersensitivity reaction that occurs from exposure to an allergen. "In a mouse model of passive systemic IgE-mediated anaphylaxis, histamine release was reduced by 43% by inhibiting STAT3." (PMID 39199166, 2024). "Short inhibition of STAT3 significantly decreases mouse and human mast cell degranulation, as well as passive systemic anaphylaxis." (PMID 34066544, 2021). "Altogether, loss of STAT3 activity has been found to reduce the incidence of anaphylaxis in humans; however, STAT3 also plays a role downstream to IFNI signaling, limiting severity of anaphylaxis in mouse models." (PMID 34066544, 2021). "Our findings that Stat1−/− mice showed normal systemic anaphylaxis and that the administration of a Stat3 inhibitor in a Stat1−/− but not WT background caused the exacerbation of anaphylaxis strongly suggested that Stat1 and Stat3 function redundantly in this process." (PMID 31730616, 2019). "Although hyper IgE may decrease the contribution of antigen-specific IgE to FcεRI cross-linking, these previous findings suggest that STAT3 positively regulates mast cell function, including degranulation, and support the idea that STAT3 inhibition is beneficial for controlling anaphylaxis." (PMID 31730616, 2019).
aplastic anemia (5 papers, 2017 to 2022). Anemia resulting from bone marrow failure (aplastic or hypoplastic bone marrow). "Interestingly, in aplastic anemia the presence of STAT3 mutations was associated with the carriership of HLA-DR15, which is a major genetic risk factor of MS." (PMID 36441748, 2022). "Besides, TPO attenuates aplastic anemia serum-induced apoptosis in the mouse myeloid progenitor cells through STAT3/STAT5 pathway." (PMID 35768562, 2022). "In this view, it has been reported that STAT3-mutant LGL clones may facilitate bone marrow failure in a subset of aplastic anemia patients and may be potentially amenable to immunosuppressive treatment." (PMID 35392224, 2022).
celiac disease (5 papers, 2021 to 2025). An autoimmune genetic disorder with an unknown pattern of inheritance that primarily affects the digestive tract. "It is interesting to note that interleukin-15 (IL15), but not IL8, can induce the transcription of NEAT1 by recruiting the signal transducer and activator of transcription 3 (STAT3) to its promoter in celiac disease (CD) patients." (PMID 40362651, 2025).
cholesteatoma (5 papers, 2015 to 2023). A pathologic process characterized by the proliferation of keratinizing squamous epithelium resulting in the accumulation of keratin and cells in the middle ear and/or mastoid. "It is also supposed that Signal transducer and activator of transcription 3 (STAT3) could play a crucial role in cholesteatoma cell growth, as well as many other processes such as autophagy, cytoskeletal organization, and apoptosis inhibition." (PMID 37623440, 2023). "In order to assess the molecular pathways involved in the induction of HaCaT or HEKA cell proliferation and proinflammatory cytokine production upon stimulation with normal control or cholesteatoma sEVs, components of the MAPKp44/p42, STAT3, and the NF-κB pathway components were examined." (PMID 37998605, 2023). "In agreement with other reports, we found that levels of pAkt and pNF-κB molecules were significantly increased and the phosphorylated forms of c-Jun, MEK1, MEK2, MAPKp44/p42 (Erk1/2), and STAT3 were overexpressed in cholesteatoma tissue vs. normal skin epithelium." (PMID 25385222, 2015). "In comparison to sEVs isolated from the plasma of controls, cholesteatoma-derived sEVs significantly enhanced keratinocyte proliferation and IL-6 production (p < 0.05), potentially by engaging multiple activation pathways including MAPKp44/p42, STAT3, and the NF-κB pathway." (PMID 37998605, 2023). "The phosphorylation of STAT3 and TGF- β expression showed the same trend, greatly increased in acquired pediatric forms as compared to other cholesteatomas." (PMID 37623440, 2023). "Eskiizmir and others found that STAT3 was positive in external auditory canal skin by immunohistochemistry but not in cholesteatoma tissue." (PMID 34696703, 2021). "The aim of our study was to analyze the expression of inflammatory (IL-1β), hyper-proliferative (STAT-3, TGF-β), and angiogenic (VEGF-C, PDGFr) factors in congenital and acquired cholesteatomas (both in adults and children), which might correlate with the clinical features observed." (PMID 37623440, 2023).
chronic granulomatous disease (5 papers, 2019 to 2023). Chronic granulomatous disease (CGD) is a rare primary immunodeficiency, mainly affecting phagocytes, which is characterized by an increased susceptibility to severe and recurrent bacterial and fungal infections, along with the development of granulomas. "It has also been described in genetically diverse IEIs including ataxia telangiectasia, NFKB1 haploinsufficiency, ADA2 deficiency, CD40 ligand deficiency, activated PI3K delta syndrome, STAT3 gain of function and chronic granulomatous disease (CGD)." (PMID 38068532, 2023).
coccidioidomycosis (5 papers, 2017 to 2025). A fungal infection caused by Coccidioides immitis. "A recent patient with disseminated coccidioidomycosis was found to have a STAT3 mutation." (PMID 38250880, 2024). "We identified 8 patients with disseminated coccidioidomycosis who had defects in the interleukin-12/interferon-γ and STAT3 axes, indicating that these are critical host defense pathways." (PMID 28098554, 2017). "The involvement of STAT3 in resistance to Coccidioides infection is complex." (PMID 28098554, 2017).
congestive heart failure (5 papers, 2019 to 2025). Failure of the heart to pump a sufficient amount of blood to meet the needs of the body tissues, resulting in tissue congestion and edema. "Furthermore, cardiac restricted overexpression of STAT3 in mice led to protection against DOX-induced atrophy and congestive heart failure, whereas cardiac specific knockout of STAT3 in mice was accompanied by increased cardiac fibrosis and age-dependent heart failure." (PMID 32411725, 2020). "In a murine model of congestive heart failure (CHF), HDAC1 and HDAC2 also contributed to MF by participating in the IL‐6/STAT3 signalling pathway." (PMID 40497340, 2025).
cryptococcal infection (5 papers, 2019 to 2022). "Monogenic mutations, such as those in the zinc transcription factor GATA2 gene, the transcriptional activator STAT3 gene, and the CD40 ligand CD40LG gene, are also associated with cryptococcosis in seronegative HIV patients (39, –, 41)." (PMID 30755511, 2019).
dementia (5 papers, 2017 to 2021). Loss of intellectual abilities interfering with an individual's social and occupational functions. "STAT3 plays an important role in learning and memory in both humans and animals, and is closely associated with cognitive dysfunction and dementia." (PMID 28915561, 2017).
diabetic neuropathy (5 papers, 2012 to 2025). A chronic, pathological complication associated with diabetes mellitus, where nerve damages are incurred due to diabetic microvascular injury involving small blood vessels that supply these nerves, resulting in peripheral and/or autonomic nerve dysfunction. "The aim of the present study was to further elucidate the role of JAK2/STAT3-CAV-1-NR2B on painful diabetic neuropathy." (PMID 30830585, 2019). "Collectively, PIAS1 can improve diabetic neuropathy by regulating the miR-124-EZH2/STAT3 pathway." (PMID 34857740, 2021). "We have previously shown that alpha-lipoic acid, a potent antioxidant used for diabetic neuropathy, enhanced DDAH activity and DDAH II gene expression through the regulation of STAT3 in cultured endothelial cells." (PMID 23284999, 2012). "Therefore, in treating diabetic neuropathy, CXCL6 appears to hold promise as a new therapeutic target and possible biomarker for JAK/STAT3 activation." (PMID 38882664, 2024).
disc degeneration (5 papers, 2019 to 2026). "For example, one study demonstrated that leptin promotes catabolic activity in rat NPCs by upregulating the expression of MMP‐1, MMP‐13, ADAMTS4, and ADAMTS5 via activation of the JAK2/STAT3 pathway, suggesting a mechanism contributing to disc degeneration." (PMID 41497807, 2025). "We establish ADGRG6 and STAT3 as novel regulators of endplate integrity of the intervertebral disc in mouse and suggest that modulation of ADGRG6/STAT3 signaling could provide robust disease-modifying targets for endplate-oriented disc degeneration in humans." (PMID 31652254, 2019). "To further define the role of STAT3 signaling on the pathogenesis of endplate-oriented disc degeneration, we next tested if systemic inhibition of STAT3 activation could ameliorate these defects in vivo." (PMID 31652254, 2019). "Finally, it will be important to determine how STAT3 signaling contributes to histopathology observed in other models of disc degeneration including models with lateral herniations and/or pathology of the nucleus pulposus or annulus fibrosus." (PMID 31652254, 2019). "Taken together, our work establishes Adgrg6 as a novel regulator of IVD endplate and growth plate integrity in the mouse and suggests that modulation of ADGRG6/STAT3 signaling could provide robust disease-modifying targets for endplate-oriented disc degeneration, in humans." (PMID 31652254, 2019). "In severe disc degeneration, RCOR2, STAT3, NOTCH1, SP1, and SART1 expression were elevated, while PRIM1 and LYAR expression levels were significantly reduced." (PMID 40799650, 2025). "Subsequent downregulation of LTF led to increased phosphorylation of JAK2 and STAT3, culminating in enhanced CEP calcification, senescence and ECM degradation, thereby contributing to disc degeneration." (PMID 39392081, 2024). "The findings showed that both JAK2 silencing and JAK inhibitor treatment effectively reduced SASP expression in senescent NPCs, underscoring the pivotal role of the JAK2/STAT3 signaling pathway in SASP regulation and highlighting its therapeutic potential in mitigating disc degeneration." (PMID 41497807, 2025).
Helicobacter infection (5 papers, 2015 to 2025). "Loss of STAT3 signaling in the gastric mucosa leads to decreased epithelial cell proliferation, atrophy, and metaplasia in the setting of Helicobacter infection." (PMID 29849601, 2018). "Furthermore, STAT3 is a crucial mediator in the generation of a cancer-favorable microenvironment in response to cytotoxin-associated antigen (CagA)-positive Helicobacter pylori (H. pylori) infection in the stomach." (PMID 29409467, 2018). "Helicobacter infection promoted ROS generation, which elevated IL-6 production and subsequent STAT3 phosphorylation in AGS cells." (PMID 40264171, 2025). "In summary, activation of Stat3 induces inflammation and IM in the setting of Helicobacter infection and cytokine stimulation triggers STAT3 activation and IM in vitro." (PMID 29849601, 2018). "Dysregulated STAT3 activation leads to VEGF overproduction and increased angiogenic phenotype in GC. c-Myc, which is overexpressed after Helicobacter infection, is a STAT3 target gene and can compensate for the role of STAT3, contributing to gastric epithelial cell proliferation." (PMID 40264171, 2025).
hematoma (5 papers, 2023 to 2025). A hematoma is a collection of blood from a vascular structure into an extravascular space. "The western blot findings indicated that NF-κB, STAT3, p38, and p52 phosphorylation was promoted in hematoma-affected tissue in response to ICH injury." (PMID 40093659, 2025). "Syk potentially mediates Th2-polarized cytokine secretion (Il-6/Il-10), Cd36 enhances hematoma resolution via Il-10/Stat3 signalling and Cd74 synergizes with MIF to amplify inflammatory cascades." (PMID 40623122, 2025). "Inhibition of either BACE1 or STAT3 alleviated adverse neuroinflammation and enhanced anti-inflammatory function and hematoma resolution in experimental ICH." (PMID 37552127, 2023). "In ICH, microglia-derived IL-10 can trigger a series of intracellular signal transduction events, activating signal transducer and activator of transcription 3 (STAT3)-dependent pathway to accelerate hematoma clearance and inhibit the production of pro-inflammatory cytokines." (PMID 40289984, 2025). "Immunofluorescence tests showed significantly higher fluorescence intensity of JAK2 and STAT3 in the blood 10 μL group on day 7 compared to the control and STAT3‐IN‐12 groups (P < 0.001), suggesting the activation of the JAK‐STAT signaling pathway after hematoma in the mPFC." (PMID 38946585, 2024).
human papillomavirus infection (5 papers, 2010 to 2023). "Similarly, activation of the transcription factor NF-κB, involving the small GTPase Rac1, was required for IL-6 production and subsequent STAT3 activation in human papillomavirus infection, indicating that link between NF-κB and IL-6 might be a common feature of DNA viruses." (PMID 35458402, 2022).
intervertebral disc degeneration (5 papers, 2023 to 2026). "Previous studies have shown that FCGR2A knockdown suppresses M1 polarization and NF-κB phosphorylation while enhancing M2 polarization and STAT3 activation in intervertebral disc degeneration models." (PMID 41602835, 2026). "Additionally, decreased levels of miR-98 initiated the STAT3 signaling cascade by increasing levels of MMP-2, pSTAT3, and STAT3, ultimately contributing to intervertebral disk degeneration." (PMID 36777190, 2023).